EGFR (epidermal growth factor receptor)
Diseases named in the same sentence as EGFR in open-access papers (continued):
Sharing a sentence is not in itself a finding about the gene and the disease.
colon carcinoma (continued). "The definition of EpEX as a ligand for EGFR is in line with recent reports on the activation of EGFR signaling after treatment with EpEX in mouse embryonic fibroblasts and in colon carcinoma cell lines." (PMID 30261040, 2018). "As shown by flow cytometry analysis on EGFR-positive human colon carcinoma cell lines Colo205 and HCT116, hu225 IgG and cetuximab bound with similar EC50 values to the target cells, demonstrating that the humanized IgG retained the EGFR binding activity." (PMID 29773864, 2018). "Functionally, miR-145, which blocked EGFR endocytosis, prolonged EGFR membrane signaling and altered responsiveness of colon cancer cells to EGFR-targeting drugs." (PMID 29459716, 2018). "Some colon cancer patients with metastatic disease have shown clinical benefits from treatment with EGFR antibodies: only 20–30% of these patients respond to EGFR inhibitors." (PMID 29652830, 2018). "Meaningfully, SRI 31215 overcomes autocrine HGF/MET signaling-mediated the primary resistance to EGFR inhibitors (cetuximab and panitumumab) in colon cancer cells." (PMID 30360560, 2018). "They showed that right-sided colon cancers had higher rates of MSI, more frequent aberrant activation of EGFR pathways, more frequent BRAF and PI3KCA mutations and an increased mutational burden compared to left-sided and rectal cancers." (PMID 29652830, 2018). "In colon cancer cells possessing BRAF (V600E) mutations, only simultaneous BRAF and EGFR inhibition achieved a significant inhibitory effect on tumor cells." (PMID 29652830, 2018). "Various target drugs, including cetuximab, bevacizumab and regorafinib, are widely used in colon cancer and are involved in targeting the EGFR signalling molecules." (PMID 30185207, 2018). "Together, these data suggest that MHYs inhibit EGFR-mediated signaling pathways in colon cancer cells expressing wild type KRAS." (PMID 30158525, 2018). "Strikingly, CAR T cells carrying a scFv targeting EGFR displayed significantly higher cytotoxic activities against colon cancer cells overexpressing miR-153 than the control." (PMID 29685162, 2018). "In summary, novel β-phenylacrylic acid derivatives have been shown to target KRAS wild-type colon cancer by inhibiting EGFR as well as generating stress responses." (PMID 30158525, 2018). "Additionally, since EGF-signaling antagonists are an important clinical tool used in treatment of several types of cancers including colon cancer, further studies are needed to determine whether tumors with A20 mutations may be potential targets for EGFR inhibition." (PMID 29718933, 2018). "In colon cancer cells HT reduces epidermal growth factor receptor (EGFR) level by promoting its degradation." (PMID 29495598, 2018). "Nonetheless, CAR T cells expressing this CAR transgene demonstrate stronger tumoricidal activity toward WT EGFR-expressing colon cancer cells with miR-153 overexpression than they do toward the cells without miR-153 overexpression." (PMID 29685162, 2018). "EGFR over expression occurs in many epithelial and solid malignancies like lung, breast and colon cancer." (PMID 29879970, 2018). "Another study of more than 10,000 tumors reported that EGFR expression was identified in approximately 45% of the left colon tumors, a finding similar to ours where 47% of patients were expressing EGFR." (PMID 29850390, 2018). "Functional ST6Gal1 on EGFR has been shown to be highly correlated with colon cancer progression and metastasis." (PMID 30187356, 2018). "Sequencing studies of KRAS are routinely performed in colon cancer patients undergoing systemic therapy as they are a contraindication to EGFR targeted therapy." (PMID 29698444, 2018). "A number of preclinical therapeutic strategies have been developed by combining EGFR pathway inhibitors with other target drugs in BRAF/KRAS mutant colon cancers." (PMID 30185207, 2018).
colon carcinoma (continued). "There was a significant difference in the expression of BRAF between the BRAF (V600E) MT and WT (p = 0.008) in colon cancers; and there was a significant difference in the expression of EGFR between the NRAS MT and WT (p = 0.021) in rectal cancers." (PMID 30416987, 2018). "EGFR plays a critical role in the process of proliferation and differentiation in colon cancer cells." (PMID 30185207, 2018). "miR-145, which inhibited EGFR endocytosis, also prolonged EGFR membrane signaling and altered responsiveness of colon cancer cells to EGFR-targeting drugs." (PMID 29459716, 2018). "Our data reveal that β-phenylacrylic acid derivatives, MHYs, function as novel EGFR inhibitors in KRAS wild-type colon cancer." (PMID 30158525, 2018). "These EGFR antagonists show considerable clinical efficacy and, in particular, their use in colon carcinoma as well as that in head and neck cancer treatment can substantially extend survival time." (PMID 28970798, 2017). "The role of endogenous CD9 in cellular proliferation appears to depend on cellular context; it has been reported to activate EGFR signalling pathways (pro-proliferative) in gastrointestinal cancer cells, but to be anti-proliferative in human colon carcinoma." (PMID 28881726, 2017). "Consistently, the upregulation of EGFR in melanoma cells results in loss of activity of BRAF inhibitors and dual inhibition of EGFR and BRAF re-establishes vemurafenib activity in colon carcinoma cells." (PMID 29033690, 2017). "This evidence is consistent with previous studies, in colon carcinoma and melanoma cells, suggesting that EGFR expression dictates the activity of BRAF inhibitors." (PMID 29033690, 2017). "Of interest, in colon carcinoma patients, EGFR antagonist treatment appears efficient only in combination with chemotherapy." (PMID 28970798, 2017). "Here, we describe the effect of two molecules, cetuximab and HT, a polyphenol from olive oil, that impair the EGF/EGFR oncogenic drive, yielding a reduced proliferation of colon cancer cells." (PMID 29137335, 2017). "Further investigation indicated that NCTD suppressed not only the expression of the total EGFR and the phosphorylated EGFR but also the expression of the total c-Met and the phosphorylated c-Met in colon cancer cells." (PMID 28086832, 2017). "An in vitro study showed that hydroxytyrosol, which is a phenolic compound present in olive oil, downregulated epidermal growth factor receptor (EGFR) expression in colon tumor cells." (PMID 28662634, 2017). "This study reveals that the expression of cell surface MUC1 is a critical enhancer of EGF-induced EGFR activation in human breast and colon cancer cells." (PMID 28731466, 2017). "Again, genes involved in Wnt signaling (in KEGG, Reactome, and WikiPathway) were up-regulated in the resistant condition in both breast and colon cancer when compared to the sensitive condition, thus contributing to acquired resistance to EGFR-TKIs." (PMID 28288164, 2017). "HPMA-copolymer conjugated with oligopeptide G11 has shown high cellular uptake in vitro in colon cancer cells with EGFR (epidermal growth factor receptor) overexpression." (PMID 28911246, 2017). "It will be interesting to determine the role of HDAC4/EGFR/ERK1/2 signaling in colon cancer expressing wild type K-Ras versus mutant K-Ras, in association with cancer progression and therapy resistance, in future studies." (PMID 29152115, 2017). "It has also been reported that Src activation plays a permissive role for PAR1-mediated transactivation of EGFR in colon cancer cell growth." (PMID 28819180, 2017). "Here we report the results of an in vivo study in three RAS WT human colon cancer xenografts as relevant models for EGFR inhibitor-sensitive mCRC to better define the anti-tumor activity of MM151 as compared to cetuximab." (PMID 29137301, 2017).
colon carcinoma (continued). "We believed that FOXD3 is likely to be an essential factor in protecting against human colon cancer formation, whose effects are mediated by EGFR-Ras-Raf-MEK-ERK signaling pathway." (PMID 27926503, 2017). "It is reported that FA inhibits EGFR-mediated proliferation in human colon cancer cells, whereas FA treatment increases in vitro growth and invasiveness of prostate cancer cells." (PMID 29070520, 2017). "Hydroxytyrosol (HT), a polyphenol of olive oil, downregulates epidermal growth factor (EGFR) expression and inhibits cell proliferation in colon cancer (CC) cells, with mechanisms similar to that activated by the EGFR inhibitor, cetuximab." (PMID 29137335, 2017). "As lapatinib sensitizes colon cancer cells to EGFR inhibitors or fluoropyrimidines, the combination of lapatinib with standard chemotherapy has been suggested as a new strategy for the treatment of metastatic colorectal cancer." (PMID 27965461, 2017). "In our study, we demonstrated that FOXD3 knockdown markedly activated EGFR-Ras-Raf-MEK-ERK signaling pathway in human colon cancer in vitro and in vivo." (PMID 27926503, 2017). "Once animals had developed hepatic colon cancer metastases, tumor sections were dissected and investigated for EGFR expression." (PMID 29190908, 2017). "To evaluate the potency of NCTD in killing colon cancer cells, we used gefinitib, the EGFR inhibitor, as the positive control." (PMID 28086832, 2017). "Conversely, the impairment of the EGF/EGFR system afforded by the HT and cetuximab combination appears to be related to its ability to mainly provoke a growth arrest in G2/M phases in colon cancer cells." (PMID 29137335, 2017). "Taken together, our data demonstrated role of the HDAC4/EGFR/ERK1/2 signaling in regulating claudin-2 expression in differentiating colon cancer cells." (PMID 29152115, 2017). "In additional studies, we identified specific role of the EGFR/ERK1/2 signaling in promoting claudin-2 expression in colon cancer cells." (PMID 29152115, 2017). "The efficacy of anti-EGFR antibodies depends on the presence of RAS/BRAF mutations and moreover, the efficacy of both anti-EGFR and anti-VEGF antibodies seems to vary between the right-sided (RS) and left-sided (LS) colon tumors." (PMID 28714940, 2017). "All together the data suggests that the combination of HT with cetuximab inhibits cell growth by targeting EGFR levels in colon cancer cells." (PMID 29137335, 2017). "Monoclonal antibodies (MABs) such as rituximab or cetuximab target more specific tumor cell antigens, the former targeting the CD20 protein in malignant lymphoma, the latter targeting epidermal growth factor receptor (EGFR) in colon cancer." (PMID 28407743, 2017). "Oxaliplatin was found to activate SRC in colon cancer cells by ROS-dependent pathway, which leads to the activation of EGFR signaling and decreasing of the effects of cetuximab." (PMID 28288572, 2017). "In this study we first tested the influence of MUC1 expression on EGFR activation in human breast epithelial and colon cancer cells and assessed the influence of MUC1 intra- and extra-cellular domains on this effect." (PMID 28731466, 2017). "Cytotoxic effects of A-PBNK (but not UCB-NK) were further potentiated significantly by coating EGFR+ colon cancer cells with cetuximab." (PMID 28220124, 2017). "Activation of the EGFR signal transduction pathway controls a variety of cellular processes essential for colon cancer progression, including tumor cell survival, proliferation and motility." (PMID 28686677, 2017). "Meanwhile, FOXD3 knockdown activated EGFR-Ras-Raf-MEK-ERK signaling pathway in human colon cancer cells and caner tissues." (PMID 27926503, 2017). "It is well known that two cell surface receptor tyrosine kinases, c-Met and EGFR, are co-present in 78% to 80% in colon cancer cells." (PMID 28086832, 2017).
colon carcinoma (continued). "Tumor specific EGFR downstream signaling mutations in KRAS, BRAF, PTEN, and PIK3CA cause reduced benefit of cetuximab therapy in colon carcinoma patients." (PMID 27100871, 2016). "FITC-CTX/GO stained the EGFR-positive human colon carcinoma cell line DLD1 cells brightly but only weakly stained a small fraction of Raji cells." (PMID 26859679, 2016). "The most straightforward utility of the colon cancer data was for predicting insensitivity to anti-EGFR antibodies." (PMID 27245685, 2016). "EGFR is overexpressed in 60-80% of colon cancers, and clinical studies of EGFR-targeted drugs have already been conducted." (PMID 27683110, 2016). "Overall, these results demonstrate that IGF-1 from colon cancer cells induced M2 macrophage polarization, and inhibition of EGFR in HCT116 cells reduced both IGF-1 secretion and HCT116 CM-induced macrophage polarization." (PMID 27683110, 2016). "Colon cancer cells express high amounts of EGFR and overexpress TGFα in response to hypoxia, triggering a signalling cascade that helps them survive." (PMID 28105072, 2016). "In conclusion, our results suggest that inhibition of the EGFR signaling pathway in colon cancer cells alters cytokine secretion (e.g. IGF-1) and prevents M1- to M2-like polarization in macrophages, thus inhibiting cancer cell growth." (PMID 27683110, 2016). "Anti-EGFR therapy in patients with KRAS WT colon tumors is standard of care, whereas patients with RAS mutant tumors are excluded." (PMID 27845624, 2016). "Patients with colon cancer who receive the epidermal growth factor receptor (EGFR) targeted antibodies cetuximab or panitumumab usually develop resistance within several months of initiating therapy." (PMID 27449290, 2016). "In this study, we found that the EGFR pathway modulated macrophage numbers and polarization in colon cancer, and consequently influenced tumor growth." (PMID 27683110, 2016). "The role of these miRNAs in EGFR signaling regulation and cetuximab outcome in colon cancer is beginning to emerge, but remains poorly explored." (PMID 26824186, 2016). "Markers that have been clinically introduced in colon cancer include RAS mutations that exclude anti-EGFR therapy and microsatellite instability (MSI) as a marker of good prognosis in stage II colon cancer." (PMID 27849044, 2016). "Epidermal growth factor receptor (EGFR) is a target of colon cancer therapy, but the effects of this therapy on the tumor microenvironment remain poorly understood." (PMID 27683110, 2016). "The EGFR expression level (ΔMFI) on the other colon cancer cell lines was 23 for CaCo-2, 7 for HT-29, and 3 for SW620 (data not shown)." (PMID 27314237, 2016). "EGFR knockout in colon cancer cells inhibited macrophage-induced promotion of xenograft tumor growth." (PMID 27683110, 2016). "For example, epidermal growth factor receptor (EGFR) targeting has been used to treat advanced colon cancer, and an anti-interleukin-6 (IL-6) receptor antibody has been used to suppress angiogenesis and inhibit CRC growth." (PMID 27384995, 2016). "SRI 31215 overcomes primary resistance to cetuximab and gefitinib in HGF-producing colon cancer cells and prevents fibroblast-mediated resistance to EGFR inhibitors." (PMID 27121052, 2016). "In primary colon tumours, aberrant TGFα/EGFR expression helps propagate tumour cells in lymph nodes and the liver." (PMID 28105072, 2016). "Inhibitors of EGFR (EGFRi), such as cetuximab and panitumumab, have been used successfully for the treatment of colon cancer patients with WT Kras." (PMID 27121052, 2016). "In this retrospective study, we evaluated common hot spot gene mutations located downstream of EGFR signaling pathway, the potential prognostic value for KRAS, BRAF, PIK3CA and NRAS was assessed in 228 stage II-III colon cancer." (PMID 27074743, 2016).
colon carcinoma (continued). "While melanoma cells require another genetic event, such as EGFR overexpression, to develop resistance, B-RafV600E-positive colon cancer cells are already resistant to Raf or MEK1/2 inhibition and do not respond to treatment with vemurafenib." (PMID 27342992, 2016). "By contrast, conditioned medium of EGFR knockout colon cancer cells inhibited expression of these M2-related markers and induced macrophage expression of the M1-related markers inducible nitric oxide synthase (iNOS), IL-12, TNF-α and CCR7." (PMID 27683110, 2016). "Epidermal Growth Factor Receptor (EGFR) activates a robust signalling network to which colon cancer tumours often become addicted." (PMID 27708224, 2016). "It was reported that EGFR signaling pathway suppressed miR-143/145 in colonic cells, while overexpression of these miRNAs suppressed EGFR-induced colon cancer cell growth." (PMID 26824186, 2016). "Bile acids have been reported to transactivate EGFR in cholangiocytes as well as colon cancer cells." (PMID 27924062, 2016). "Recently, it was suggested that the growth of BRAF-mutant colon carcinoma cell lines can be inhibited by combining a BRAF inhibitor with an EGFR inhibitor, which both were suggested to be inactive as single agents." (PMID 26018524, 2015). "Our data show that, in colon carcinoma TAFs, chronic Celecoxib treatment exerts a complex control on EGFR levels, activity and turnover." (PMID 25987127, 2015). "HGUE-C-1 cells were also treated in culture with cetuximab, an antibody against the extracellular domain of EGFR, since this is a treatment used in advanced colon carcinoma patients and since HGUE-C-1 cells are wild type for KRAS and BRAF." (PMID 25885658, 2015). "The invasiveness and metastasis functions of KITENIN were shown to be mediated by ERK/AP-1 activation through the interaction of KITENIN with Dvl/PKCδ or the KITENIN/ErbB4-Dvl2-c-Jun axis, as an EGFR-independent EGF signal in colon cancer cells." (PMID 25605251, 2015). "It has been demonstrated that EGFR is frequently deregulated in human tumors, such as prostate and colon tumors, triggering downstream oncogenic signaling pathways." (PMID 25860930, 2015). "It has been reported that TLCA induced growth of colon cancer cells through the M3 mAChR-transactived EGFR signaling pathway." (PMID 25815516, 2015). "It has been reported that colon cancer patients with KRAS and BRAF mutations that lie downstream of epidermal growth factor receptor (EGFR) acquire resistance against therapy with anti-EGFR antibodies, cetuximab and panitumumab." (PMID 25936694, 2015). "We recently found that HDAC inhibitors (HDACi) act through transcription inhibition to induce EGFR down-regulation and growth inhibition in colon cancer cells." (PMID 25980579, 2015). "Recently, miR-147 was found to be able to induce a MET and reverses EGFR inhibitor resistance in colon cancers." (PMID 26064956, 2015). "Several resistance mechanisms to EGFR inhibitors are clinically validated in lung and colon cancers and are likely applicable to OSCC." (PMID 26462152, 2015). "It has been reported that the LGG-derived protein p40 up-regulates Muc2 gene expression and increases mucus production through transactivation of EGFR/Akt signaling in LS174T human colon cancer cells." (PMID 25915861, 2015). "In colon cancer cells blockade of EGFR by the antibody cetuximab or by EGFR small molecule inhibitors such as gefitinib or erlotinib proves strongly synergistic with BRAFV600E inhibition in suppressing MAPK signaling and reducing cell viability." (PMID 26023796, 2015). "It has been reported that some forms of bile acids, including DCA, LCA, GDCA, TDCA, GLCA and TLCA, induced growth of colon cancer cells, through the M3 mAChR-transactived EGFR signaling pathway." (PMID 25815516, 2015). "These EGFR mAbs are active, mostly in combination with cytotoxic drugs, both in the first line of therapy and in previously treated patients with colon cancer." (PMID 26491668, 2015).